HRH2 (histamine receptor H2)
Diseases named in the same sentence as HRH2 in open-access papers:
HRH2 is named in the same sentence as 120 diseases in open-access papers, as found by Europe PMC text mining. Sharing a sentence is not in itself a finding about the gene and the disease. The quoted sentences say what the papers report.
gastroesophageal reflux disease (20 papers, 2015 to 2025). A chronic disorder characterized by reflux of the gastric and/or duodenal contents into the distal esophagus. "Over the counter HRH2 blockers, such as cimetidine (Tagamet®) and famotidine (Pepcid®), are used to reduce gastric acid secretion and treat peptic ulcers and acid reflux." (PMID 37366936, 2023). "Histamine receptor 2, HRH2, is involved in gastric acid secretion and gastroesophageal reflux diseases (GERD)." (PMID 37366936, 2023).
Peptic ulcer (20 papers, 2008 to 2025). The term peptic ulcer refers to acid peptic injury of the digestive tract, resulting in mucosal break reaching the submucosa. "Histamine receptor 2 (HRH2) blockers are used to treat peptic ulcers and gastric reflux." (PMID 37366936, 2023).
gastric ulcer (9 papers, 2015 to 2024). An ulcerated lesion in the mucosal surface of the stomach. "Histamine receptor-2 (HRH2) in particular is associated with gastric ulcers such that HRH2-blockers, such as rantidine (Zantac), are used to treat conditions involving excessive stomach acid production." (PMID 39146372, 2024).
melanoma (9 papers, 2008 to 2025). A malignant, usually aggressive tumor composed of atypical, neoplastic melanocytes. "HRH2 are found in human mammary and gastric carcinoma cells and several human melanoma cell lines and the HRH2 antagonist cimetidine appears to be endowed with anticancer properties, although its action is not exclusively mediated through HRH2." (PMID 24662753, 2014). "Finally, downregulation of HRH2 (histamine receptor H2) could be indicative of tumor metastasis in the context of immune failure, as a balance of histamine with its receptor is necessary to either stimulate or suppress the growth of melanoma." (PMID 38023136, 2023). "In tumor‐bearing mice, histamine was found to promote melanoma growth primarily through histamine receptor H1 (HRH1), rather than histamine receptor H2 (HRH2)." (PMID 41085102, 2025).
Allergy (8 papers, 2019 to 2025). An allergy is an immune response or reaction to substances that are usually not harmful. "Histamine receptors are classified into four subtypes, with HRH1 and HRH2 being targets of anti-allergy and antiulcer drugs, respectively." (PMID 36246574, 2022). "The up-regulated genes have been previously associated with asthma; hyper-reactivity and allergy (CCR2, HRH2, PTEN); lung development and apoptosis (CHRNA7, RTKN2); and immune function (GIMAP4, GIMAP7, KLRC3 and CD99)." (PMID 30971730, 2019). "However, the differences between those with allergic diseases and healthy children observed at the gene expression level were not confirmed on the protein level of NT-3, NT-4, and HRH2." (PMID 32596360, 2020).
COVID-19 (7 papers, 2021 to 2024). A disease caused by infection with severe acute respiratory syndrome coronavirus 2. "We propose that the principal mechanism of action of famotidine for relieving COVID-19 symptoms involves on-target histamine receptor H2 activity, and that development of clinical COVID-19 involves dysfunctional mast cell activation and histamine release." (PMID 33833683, 2021). "The most straightforward explanation of the apparent famotidine activity as a COVID-19 therapy is that the drug acts via its antagonism or inverse-agonism of histamine signaling and via its arrestin biased activation—all a result of famotidine binding to histamine receptor H2." (PMID 33833683, 2021).
gastric cancer (5 papers, 2012 to 2022). A primary or metastatic malignant neoplasm involving the stomach. "Based on GEPIA, hrh2, the same as ghrl, is a survival gene in gastric cancer whose underexpression is associated with better survival in patients (downregulated based on our DEGs)." (PMID 35650297, 2022). "Therefore, the influence of HRH2 genotype on methylation status of non-cancerous mucosa in patients who have already developed gastric cancer may be indistinct." (PMID 23280118, 2013).
schizophrenia (5 papers, 2013 to 2022). A major psychotic disorder characterized by abnormalities in the perception or expression of reality. "HRH2 reactivities were observed in 15 schizophrenia subjects and 14 control samples." (PMID 33208725, 2020). "Famotidine, an HRH2 antagonist, significantly reduced psychotic symptoms in schizophrenia patients." (PMID 31481665, 2019).
breast carcinoma (4 papers, 2015 to 2024). "In summary, to our best knowledge, this work is the first study addressing the relationship between HRH2 gene polymorphism and risk of breast cancer." (PMID 25922853, 2015). "Histamine H2 receptor (HRH2) was previously suggested to affect the proliferation of breast cancer cells and disease-free survival of breast cancer patients." (PMID 25922853, 2015). "Additionally, HRH2 expressed in other cells (e.g., fibroblasts) was also reported to mediate important effects on the epithelial-to-mesenchymal transition progress of breast cancer cells." (PMID 25922853, 2015). "Furthermore, activation of HRH2 in breast cancer cells was reported to increase tumor proliferation and blocking HRH2 was suggested to improve disease-free survival in breast cancer patients." (PMID 25922853, 2015). "In addition, HRH2 activation in breast cancer cells was suggested to increase tumour proliferation, whereas blocking HRH2 was reported to improve disease‐free survival in breast cancer patients." (PMID 29675884, 2018). "Therefore, the goal of the present study was to demonstrate the relationship between rs2067474 of HRH2 and breast cancer risk by using case-control method among Chinese Han population, hoping to provide further insights into the effect of HRH2 on the development of breast cancer." (PMID 25922853, 2015). "Therefore, since genetic association investigation does not involve the application of any HRH2 antagonists, our present findings may be more persuasive regarding the direct effect of HRH2 on breast cancer compared with previous investigations." (PMID 25922853, 2015). "Therefore, elucidating this issue might provide better understandings of how HRH2 affects the development of breast cancer." (PMID 25922853, 2015). "The interactions are visually represented in a diagram, showing that HRH1, HRH2, and HRH4 are central to the network, indicating their significant roles in breast cancer pathology." (PMID 39267843, 2024). "However, no statistical association was observed regarding rs2067474 in this study, which indicates that this HRH2 gene polymorphism might not be a risk factor in the development of breast cancer in Chinese Han population." (PMID 25922853, 2015).
colon cancer (2 papers, 2023 to 2024). "Another study stated that HRH4 expression in CRC tissue and normal colon mucosa was present, and HRH1, HRH2, and HRH4 in human colon cancer cells: HT29, Caco-2, and HCT116." (PMID 36902343, 2023).
hepatocellular carcinoma (2 papers, 2016 to 2021). A malignant tumor that arises from hepatocytes. "HRH2 KO hepatoma cells showed decreased cell proliferation, and increased sensitivity to oxidative stress and apoptosis compared to cells expressing a sgCTRL." (PMID 34535664, 2021).
kidney cancer (2 papers, 2008 to 2022). Primary or metastatic malignant neoplasm involving the kidney. "We observed that the mRNA expression level of ETV4 was significantly increased and the expression levels of SH2B3, FATE1, GRK5, MALL, HRH2, SEMA3G and SLC10A6 were decreased prominently in kidney cancer cells when compared with HK2 cell line." (PMID 36059531, 2022). "Furthermore, we detected the mRNA and protein expression levels of 8 epi-PCGs (ETV4, SH2B3, FATE1, GRK5, MALL, HRH2, SEMA3G and SLC10A6) in 4 human kidney cancer cell lines (786-O, A498, Caki-1 and ACHN) and the normal human renal tubular epithelial cell line HK2." (PMID 36059531, 2022).
liver disease (2 papers, 2021 to 2022). "It has been found that the HRH2 blocker nizatidine can be used for treating advanced liver disease and liver cancer, and is a potential clinical target for liver cancer treatment." (PMID 36059531, 2022). "Collectively, these genetic loss-of-function studies suggest that HRH2 plays a functional role in hepatocarcinogenesis, and that the biological effects of nizatidine on liver disease progression are likely mediated by HRH2." (PMID 34535664, 2021). "Collectively, these results support a functional relevance of the HRH2 pathway in pan-etiology liver disease progression and hepatocarcinogenesis in patients." (PMID 34535664, 2021). "By improving liver inflammation, fibrosis, and anticancer surveillance, HRH2-targeting compounds provide a therapeutic candidate approach for patients with fibrotic liver disease at risk for HCC and will guide future optimization of refined HRH2-targeting liver disease therapies." (PMID 34535664, 2021). "By combining our system and validation in rodent and patient-derived models, we discover nizatidine, a histamine receptor H2 (HRH2) blocker, for treatment of advanced liver disease and HCC chemoprevention." (PMID 34535664, 2021). "Using the PLS as a readout, followed by validation in nonalcoholic steatohepatitis/fibrosis/HCC animal models and patient-derived liver spheroids, we identify nizatidine, a histamine receptor H2 (HRH2) blocker, for treatment of advanced liver disease and HCC chemoprevention." (PMID 34535664, 2021).
atrial fibrillation (1 paper, 2013). A disorder characterized by an electrocardiographic finding of a supraventricular arrhythmia characterized by the replacement of consistent P waves by rapid oscillations or fibrillatory waves that vary in size, shape and timing and are accompanied by an irregular ventricular response. "We demonstrate the use of our algorithm to predict novel candidate genes for human atrial fibrillation (such as HRH2, ATP4A, ATP4B, and HOPX) and epilepsy (e.g., PAX6 and NKX2-1)." (PMID 23800157, 2013).
autism spectrum disorder (1 paper, 2021). A spectrum of developmental disorders that includes autism, and Asperger syndrome. "Histamine dysregulation may have a role in mediating autism spectrum disorder phenotype with altered expression of key histamine signaling genes HNMT, HRH1, HRH2, and HRH3 in post-mortem brains of patients with ASD." (PMID 34335160, 2021).
cholangiocarcinoma (1 paper, 2025). A carcinoma that arises from the intrahepatic biliary tree (intrahepatic cholangiocarcinoma) or from the junction, or adjacent to the junction, of the right and left hepatic ducts (hilar cholangiocarcinoma). "HRH2 and HGF were primarily expressed in CAFs within the tumor microenvironment of cholangiocarcinoma." (PMID 41048570, 2025).
colonic adenocarcinomas (1 paper, 2016). "At week 18, feeding with the diets containing cimetidine (Hrh2 antagonist) and clobenpropit (Hrh3 antagonist/inverse agonist) significantly lowered the multiplicity of colonic adenocarcinoma." (PMID 26907350, 2016). "The mean MCM2-positive indices of colonic adenocarcinomas in groups 3 (p < 0.001) and 4 (p < 0.001) were significantly lower than that of group 1, indicating that dietary administration with Hrh2 and Hrh3 antagonists decreased cancer cell proliferation." (PMID 26907350, 2016).
endometrial cancer (1 paper, 2021). Primary or metastatic malignant neoplasm involving the endometrium (mucous membrane that lines the endometrial cavity). "The analysis showed that the expression of HRH1, HRH2, and HRH3 increased with the progression of endometrial cancer." (PMID 34768392, 2021).
endometriosis (1 paper, 2025). The growth of functional endometrial tissue in anatomic sites outside the uterine body. "This pattern—reduced overall CD45-positive cell density combined with increased HRH2/HRH3 colocalization—suggests that deep infiltrating endometriosis may harbor a qualitatively distinct immune infiltrate compared with the other lesion types." (PMID 41516088, 2025). "This pattern suggests that histamine signaling via HRH1 and HRH2 may influence both nociceptive and autonomic components within deep infiltrating endometriosis lesions." (PMID 41516088, 2025). "Specifically, HRH2 and HRH4 were detected in nerve fibers of peritoneal endometriosis, whereas HRH1–HRH3 were expressed in nerve fibers of deep infiltrating endometriosis." (PMID 41516088, 2025). "Nevertheless, colocalization of HRH2 and HRH3 with CD45 was higher in this endometriosis tissue (HRH2: 0.34, 0.00–1.55; HRH3: 0.23, 0.05–0.47) than in control tissues (both 0.00, 0.00–0.00; p = 0.034 and p = 0.012, respectively)." (PMID 41516088, 2025). "The presence of HRH2- and HRH3-positive fibers within both sensory and autonomic systems in deep infiltrating endometriosis suggests that histamine may also contribute to visceral dysregulation and autonomic dysfunction, components increasingly recognized in endometriosis-associated pain syndromes." (PMID 41516088, 2025). "Using gene expression data from the database provided by the University of Turku, we analyzed the expression levels of histamine receptors HRH1, HRH2, HRH3, and HRH4 across various endometriosis subtypes and control tissues." (PMID 41516088, 2025). "In deep infiltrating endometriosis tissues, HRH1-, HRH2-, and HRH3-positive nerve fibers were identified in 15.63%, 52.17%, and 28.95% of nerves, respectively, whereas ovarian endometriosis showed no receptor-positive nerve fibers." (PMID 41516088, 2025).
hyperprolactinemia (1 paper, 2023). Abnormally high level of prolactin in the blood. "The HRH2 activity noted herein may therefore contribute to the ADR of hyperprolactinemia reported in SIDER." (PMID 37468498, 2023).
Infant Respiratory Distress Syndrome (1 paper, 2021). "A significantly decreased number of NEC infants presented Infant Respiratory Distress Syndrome (38% vs. 57.6%) and were administered Histamine Receptor H2 block (p < 0.01, Table A2)." (PMID 33804829, 2021).
intestinal cancer (1 paper, 2016). "Although some Hrh2 antagonists, such as ranitidine and famotidine, were found to lack tumor-inhibitory effects, cimetidine was able to suppress the growth of CRC implants in mice, chemically-induced intestinal cancers in rats and human CRC by inhibition of angiogenesis." (PMID 26907350, 2016).
lung carcinoma (1 paper, 2022). "Only the expression of GPR54 was associated with CD8+ T cell infiltration in lung cancer, although Grin1 (glutamate receptor), Ptger1 (prostaglandin E receptor 1), Hrh2 (histamine receptor), Ghsr (growth hormone secretagogue receptor), and Tacr1 (substance P receptor) were detected." (PMID 35224894, 2022).
oral cancer (1 paper, 2022). "Taken together, downregulated levels of HRH4 together with upregulated levels of HRH1 and HRH2 may play critical roles in tumorigenesis of oral cancer." (PMID 35587368, 2022).
viral hepatitis (1 paper, 2021). An acute or chronic inflammation of the liver parenchyma caused by viruses. "Transcriptome profiling revealed that HRH2 and CREB5 expression were increased in viral hepatitis and NASH, confirming involvement of the pathway in disease progression across the major etiologies." (PMID 34535664, 2021).
tumor (21 papers, 1979 to 2026). "Histamine receptors, particularly HRH1 and HRH2, have been implicated in tumor growth, angiogenesis, invasion, and metastasis." (PMID 39267843, 2024). "A direct effect of nizatidine treatment on pro-inflammatory cytokine expression was confirmed in THP1-derived macrophages with similar effects of other HRH2 blockers, as well as patient-derived Kupffer cells and patient-derived tumor associated macrophages." (PMID 34535664, 2021). "Based on the previous studies, the upregulated levels of HRH1/HRH2 and tumor-associated MCs may play crucial roles in promoting tumorigenesis and progression of OSCC." (PMID 35587368, 2022). "To verify the bioinformatic findings, we performed immunohistochemical staining for HGF and HRH2 on tumor tissues from iCCA (n = 10), pCCA (n = 10), and dCCA (n = 10), with subsequent correlation analysis showing a positive correlation between their expression." (PMID 41048570, 2025). "In our study, we have identified that HRH2 and HGF were mainly expressed in CAFs within the CCA tumor microenvironment." (PMID 41048570, 2025). "At the protein level, we observed significantly higher concentrations of HRH1, HRH2, and HRH4 in tumor tissues than those in control tissues (p < 0.05)." (PMID 39267843, 2024).
cancer (19 papers, 2013 to 2025). A tumor composed of atypical neoplastic, often pleomorphic cells that invade other tissues. "Furthermore, a common polymorphism, rs2067474, was identified in an enhancer element of the HRH2 gene promoter and was reported to be associated with various diseases including cancer." (PMID 25922853, 2015). "It confirms also that WASF2 is a main mediator of cancer progression via the histaminergic system with HRH2 in the CRC." (PMID 36902343, 2023). "The therapeutic effect of nizatidine was mediated by two complementary mechanisms:Hepatocytes/parenchymal cancer cells: we demonstrate that the HRH2/CREB5 signaling pathway is perturbed in hepatocytes during liver injury." (PMID 34535664, 2021). "In contrast, cleaved caspase-3 positivity in adenocarcinomas that developed in groups 3 (p < 0.001) and 4 (p < 0.001) was significantly higher than that of group 1, suggesting the induction of apoptosis by dietary Hrh2 and Hrh3 antagonists in the cancer cells." (PMID 26907350, 2016). "Moreover, we show that HRH2 is involved in cancer cell proliferation." (PMID 34535664, 2021). "Correlation analysis also shows that the following histaminergic transcripts: GNA15, HRH2, MAOA, WASF2, and those related to inflammation: AEBP1, CXCL1, 2, 3, and 8, SPHK1, and TNFAIP6 play an important role in cancer tissue." (PMID 36902343, 2023). "Changes in DRD3 levels along with GDNF, GNAL, HRH2, CAV2, and DLG4 were characteristic of G1 cancer." (PMID 34768458, 2021). "A decrease in expression regardless of cancer grade was observed for CALM2, DRD5, ICAM1, while EGR1, HRH1, HRH2, HRH3 were overexpressed." (PMID 34768392, 2021). "High expression of EDN1, HRH2, and HRH4 promoted worse OS in non-luminal HER2+ cancers." (PMID 39267843, 2024).
infection (5 papers, 2013 to 2021). The state of being infected such as from the introduction of a foreign agent such as serum, vaccine, antigenic substance or organism. "Furthermore, the expression of the histamine receptor HRH2, which is responsible for parietal cell activation, was not affected by the infection, except on 6 dpi where a small increase was observed." (PMID 24330735, 2013).
adenocarcinoma (1 paper, 2016). A common cancer characterized by the presence of malignant glandular cells. "Adenocarcinoma cells immunohistochemically expressed Hrh1, Hrh2, Hrh3 and Hrh4 with varied intensities." (PMID 26907350, 2016).
brain diseases (1 paper, 2016). "These included Ihh (Indian hedgehog; CvN), related to “cell–cell adhesion” and “brain diseases”, Hrh2 (histamine receptor H2; CvA), and Htr2c (serotonin receptor 2C; CvI), both related to important categories of GO processes and diseases." (PMID 27782041, 2016).
HRH2 also shares sentences with these, for which no sentence is quoted: heart failure (10 papers); duodenal ulcer (9); asthma (4); atrophic gastritis (4); chronic heart failure (4); colitis (4); colorectal cancer (4); dyspepsia (4); gastritis (4); Hypertension (4); ulcer (4); Anxiety (3); atopic dermatitis (3); cardiovascular diseases (3); Parkinson disease (3); Sepsis (3); allergic rhinitis (2); anaphylaxis (2); Cognitive decline (2); delirium (2); depression (2); endometrioid adenocarcinoma (2); gastrointestinal disease (2); glioma (2); Hypomagnesemia (2); migraine (2); multiple sclerosis (2); narcolepsy (2); urticaria (2); acute coronary syndrome (1).
A further 60 diseases each share a sentence with HRH2 in 1 paper.